NRG1 (neuregulin 1)
Diseases named in the same sentence as NRG1 in open-access papers (continued):
Sharing a sentence is not in itself a finding about the gene and the disease.
schizophrenia (continued). "Type IV Nrg1 expression was not significantly increased in GABAergic interneurons from schizophrenia PFC, suggesting a specificity for an increase of type I Nrg1 expression in GABAergic interneurons." (PMID 33436636, 2021). "Our study demonstrates that Nrg1 modulates acute and long-term neurobehavioural effects of CBD, which does not reverse the schizophrenia-relevant phenotypes." (PMID 22509273, 2012). "Here we demonstrate that Nrg1 modulates acute and long-term neurobehavioural effects of CBD, which does not reverse the schizophrenia-relevant phenotypes." (PMID 22509273, 2012). "However, a follow-up study failed to report changes in NRG1, DTNBP1, or GNAO1 in patients with schizophrenia vs. controls." (PMID 23805071, 2013).
breast carcinoma (96 papers, 1995 to 2026). "To explore additional potential therapeutic targets and facilitate comprehensive treatment decisions, we analyzed actionable mutation profiles in patients with NRG1 fusions across lung cancer, colorectal cancer, and breast cancer." (PMID 40730881, 2025). "In breast cancer, the incidence of NRG1 fusion was reported to be 0.35%, with an associated adverse prognosis." (PMID 38173003, 2024). "Our findings highlight the hyperglycemia-linked epigenetic modulation of NRG1 as a potential therapeutic strategy for treating breast cancer patients with diabetes." (PMID 36707514, 2023). "Recently activation of HER3 in luminal breast cancers has been shown to be mediated in a paracrine manner by cancer-associated fibroblasts (CAFs) expressing HER3′s ligand NRG1." (PMID 36551663, 2022). "Here we show that phosphorylation and activation of HER3 in luminal breast cancer cells occurs in a paracrine manner and is mediated by NRG1 expressed by cancer-associated fibroblasts (CAFs)." (PMID 33692466, 2021). "NFKAPPAB65 (NF-kB p65 subunit) has been previously associated with stroke and the effects of NRG-1 in breast cancer and neuronal myelination, so we further investigated the role of NF-kB in NRG-1-mediated neuroinflammation." (PMID 27596278, 2016). "In these studies, it appears that NRG-1 signals by activating NF-kB p65; however, the activation of NF-kB by NRG-1 in breast cancer cells is associated with the increased expression of anti-apoptotic genes." (PMID 27596278, 2016). "Others have found loss of expression and hypermethylation of the NRG1 promoter in breast cancer cell lines that, similar to bladder, commonly show 8p alterations." (PMID 21364580, 2011). "Furthermore, through the NRG1-HER3 signaling axis, NRG1 contributes to malignant tumor development in certain cancer types, including gastric, pancreatic, and breast cancer, and its overexpression is closely associated with poor prognosis." (PMID 36707514, 2023). "Moreover, we show there is potentially clinical importance in understanding both the PIK3CA mutational status and levels of neuregulin-1 expression in patients with HER2-amplified breast cancer treated with targeted therapy and that these problems warrant further pre-clinical and clinical testing." (PMID 34344439, 2021). "Our results revealed multiple potential drug targets in NRG1 fusion patients with lung cancer, colorectal cancer, and breast cancer." (PMID 40730881, 2025). "The frequencies of NRG1 fusion in prostate cancer, breast cancer, lung cancer, and esophageal cancer were greater than the overall frequency of 0.2%." (PMID 40730881, 2025). "In this study, NRG1 fusions were observed in lung cancer, colorectal cancer, breast cancer, gastric cancer, liver cancer, esophageal cancer, pancreatic cancer, prostate cancer, and medulloblastoma." (PMID 40730881, 2025). "NRG1 rearrangement was initially reported in a breast cancer cell line and in 2014, NRG1 gene fusions were identified as activating genomic alterations in invasive mucinous adenocarcinomas of the lung." (PMID 38173003, 2024). "In fact, NRG1 fusions are considered as oncogenic drivers, occurring in 0.2% of all solid tumors and about 0.2% in breast cancers." (PMID 38360930, 2024). "The trial also assessed zenocutuzumab treatment outcomes in other NRG1+ tumors, including pancreatic and breast cancer (see their details in the corresponding sections below)." (PMID 38627681, 2024). "Here, the authors show that epigenetic regulation of Nrg1 gene during hyperglycemia promotes breast cancer development." (PMID 36707514, 2023). "Collectively, our results indicated that high-NOTCH breast cancer patients had high NRG1 levels, and elevated NOTCH activity is found in hyperglycemic breast cancer patients." (PMID 36707514, 2023).
breast carcinoma (continued). "We previously reported that Nrg1 isoform type 1 (referred to here as Nrg1) is expressed at low levels in breast cancer cells, and its overexpression is switched on under hyperglycemic conditions." (PMID 36707514, 2023). "Since the NRG1-HER3 axis is implicated in resistance to HER2-targeted therapy, the impact of NRG1 levels was investigated in HER2-positive breast cancer patients instead of the whole TCGA breast cancer cohort." (PMID 36707514, 2023). "Hyperglycemia induces Neuregulin 1 (Nrg1) overexpression in breast cancer, which subsequently promotes tumor progression." (PMID 36707514, 2023). "The addition of the mitogen Neuregulin 1 to the breast cancer organoid medium not only enables the efficient establishment of breast cancer organoids but also facilitates their long-term expansion for multiple passages." (PMID 36979752, 2023). "Neuregulin 1 (Nrg1) is a key mediator linking hyperglycemic memory in breast cancer cells with malignant tumor progression." (PMID 36707514, 2023). "Conversely, NRG1 is also considered a tumor-suppressor gene as it is inactivated in most human breast cancer cells by DNA hypermethylation of the NRG1 promoter region but is expressed in normal human mammary epithelial cells." (PMID 36707514, 2023). "As a mechanism, another study showed that fulvestrant treatment enhances the HER3 expression as well as activation in an NRG1-dependent manner in breast cancer cells." (PMID 37947595, 2023). "Our data suggest that Notch signals play a crucial role in hyperglycemia-induced Nrg1 overexpression in various breast cancer cells, resulting in malignant tumor growth." (PMID 36707514, 2023). "Consistent with active histone marks status, chromatin accessibility of the Nrg1 enhancer (+200 bp) was also increased by HG treatment in breast cancer cells, suggesting that HG resulted in an open chromatin landscape within the Nrg1 enhancer region." (PMID 36707514, 2023). "For our in vitro experiments, mouse mammary tumor cell lines Met1, 4T1, and Eo771 were maintained in media containing LG for three days, and Nrg1 levels were monitored in 4T1 cells during the adaptation period." (PMID 36707514, 2023). "Our results pave the way towards the development of novel anticancer strategies for basal-like breast cancer patients based on the interception of the NRG1/ERBB3/ERBB2 signaling axis." (PMID 35406375, 2022). "Overall, NRG1 appears to induce undesired effects on HER2+ breast cancer cells, ranging from increased proliferation and motility, and resistance to anti-ERBB2 agents." (PMID 35664762, 2022). "Intriguingly, treatment with NRG1 on two HER2+ breast cancer cellular models, namely BT474 and SKBR3 cells, unveiled an opposite response on cell proliferation." (PMID 35664762, 2022). "CAF-derived NRG1 (an HER3 ligand) causes resistance to trastuzumab, TKIs, and T-DM1 in HER2-positive breast cancers." (PMID 35326670, 2022). "We suggest that the NRG1/ERBB3/ERBB2 pathway promotes the anchorage-independent growth of basal-like breast cancer cells." (PMID 35406375, 2022). "We also tested the effects of trastuzumab and pertuzumab on the HER2/HER3 heterodimer landscape of HER2+ breast cancer cell lines provided with a saturating concentration of neuregulin-1." (PMID 35158800, 2022). "Overall, our data suggest that NRG1 induces the proliferation of SKBR3 (HER2+) breast cancer cells, and partially or completely impairs the efficacy of anti-ERBB2 agents." (PMID 35664762, 2022). "Previous findings on the relationship between PAK1 and NRG1 have been mainly reported in breast cancer cells and tumor cell lines." (PMID 35625715, 2022). "The NRG1 was originally extracted from breast cancer cells, and was subsequently extracted from the bovine brain and pituitary gland." (PMID 33897409, 2021). "We have recently shown that CAFs in luminal breast cancer can be clustered based on their expression of NRG-1." (PMID 34298736, 2021).
breast carcinoma (continued). "Using primary CAFs derived from tumour tissue of luminal breast cancer patients, we demonstrate how heterogeneous expression of NRG1 in CAFs determines response of cancer cells to therapies blocking the HER3 signaling pathway." (PMID 33692466, 2021). "In our study, we show that in luminal breast cancer, the stromal compartment is the major contributor of NRG1 expression and that its expresion is non detectable in cancer cells." (PMID 33692466, 2021). "Several lines of evidence indicate that NRG1 contributes to the development and progression of different tumour types and its expression has been correlated with poor prognosis in breast cancer, head and neck squamous cell carcinoma and pancreatic cancer." (PMID 33692466, 2021). "Taken together, these analyses uncover HAS2 as a stromal gene highly correlated with NRG1 in luminal breast cancer patients." (PMID 33692466, 2021). "And NRG1 expression is pro-apoptotic when cDNAs are transfected into cells, including the breast cancer cell line MCF7." (PMID 33413557, 2021). "Our results suggest that in luminal breast cancer, cancer cells depend on paracrine NRG1 to activate downstream pathways." (PMID 33692466, 2021). "In breast cancer, our group has shown that a subset of fibroblasts in the luminal subtype is characterised by the expression of NRG1, whose expression correlated with HAS2 expression." (PMID 34298736, 2021). "We also confirmed that similar fusions—coding sequence of another gene splicing into genomic exon 3 of NRG1—are found in breast cancers, supporting the use of this fusion as a model example." (PMID 33413557, 2021). "Strikingly, phosphorylation of the transcription factor c-JUN, described as a central molecular mediator in fibrotic conditions and hyperactivated in high density stroma breast cancer tissue, was higher in high-NRG1 CAFs (CAF#2, CAF#3, CAF#6)." (PMID 33692466, 2021). "The NRG1 fusion transcript of breast cancer cell line MDA-MB-175 was originally described as a fusion of DOC4 (now TENM4, encoding teneurin transmembrane protein 4, also called ODZ4) to NRG1." (PMID 33413557, 2021). "Reducing NRG1 expression by small interfering RNA increased cell proliferation in both normal and human breast cancer cells, whereas expression of NRG1 induced apoptosis via the downregulation of the BCL2 apoptosis regulator." (PMID 34068503, 2021). "We show here firstly that the NRG1 fusion of the breast cancer cell line MDA-MB-175, which serves as a model NRG1 fusion, is more complex than previously reported." (PMID 33413557, 2021). "In preclinical studies, NRG-1 was also protective against doxorubicin-induced or trastuzumab-induced cardiotoxicity, a common unwanted side-effect related to drugs used in breast cancer patients." (PMID 33591377, 2021). "The NRG1 fusion expressed in the breast cancer cell line MDA-MB-175 serves as a model example of such fusions, showing the proposed autocrine loop and exceptional drug sensitivity." (PMID 33413557, 2021). "Here, we used primary fibroblasts isolated from luminal breast cancer tissue and demonstrated that NRG1 produced and secreted by CAFs is sufficient to activate the HER3 pathway in cancer cells." (PMID 33692466, 2021). "Here, we have identified heterogeneous expression of NRG1 in the stroma of luminal breast cancer tissue." (PMID 33692466, 2021). "A further 20 of the first 250 breast cancer cases had breakpoints within NRG1 by DNA sequencing, 13 of which had multiple breakpoints, which would make fusion prediction difficult." (PMID 33413557, 2021). "Another study found the NRG1/EGFR interaction to be critical for the promotion of proliferation in breast cancer cells." (PMID 32552913, 2020). "In line with previous research, we confirmed here that NRG1 is downregulated in breast cancer tissues, with detrimental effects on long-term survival." (PMID 33216733, 2020).
breast carcinoma (continued). "Next, we examined the effects of anti-HER3 mAbs on the cell growth of NRG1-treated BT474 human breast cancer cells." (PMID 32002122, 2020). "Recently, a recipe based on a key addition of Neuregulin-1 to the culture medium allowed for the culture of > 80% of human breast cancer biopsies." (PMID 31829259, 2019). "We first examined how normal human breast epithelial cells from four different reduction mammoplasties responded to a breast cancer culture medium containing the essential components of Neuregulin-1 and the ROCK inhibitor Y-27632." (PMID 31829259, 2019). "NRG1 is well recognized to induce HER2-HER3 dimer overexpression not only in HER2 positive breast cancer but also in HER2 positive gastric cancer." (PMID 29535422, 2018). "In order to knock down expression of NRG1 in the MDA-MB 231 breast cancer cell line, we used the TRIPZ doxycycline-inducible vector containing either short hairpin (sh)RNAs targeting the NRG1 gene or a control empty vector." (PMID 29636067, 2018). "In this context, one of the first traceable publications described a chromosomal translocation involving the TENM4 and NRG1 (Neuregulin-1) genes in a breast cancer cell line." (PMID 30618566, 2018). "A very recent study revealed that high NRG1 expression predicts a decreased recurrence-free survival in HER2-overexpressing breast cancer patients compared to patients with low NRG1 expression, suggesting the clinical importance of NRG1." (PMID 25691057, 2015). "Similar to our findings, increased NRG-1 secretion has been attributed to gefitinib resistant breast cancer cells, and recently NRG-1 rendered cells insensitive to trastuzumab-DM1." (PMID 25344208, 2014). "Here, we determined HER1-4 receptor and neuregulin-1 (NRG1) ligand mRNA expression levels in breast cancers and corresponding normal breast tissue from patients previously characterized for plasma and tissue estrogen levels." (PMID 23991224, 2013). "In breast cancer, several breakpoints have been identified close to or within NRG1 and recent identification of promoter hypermethylation suggests a possible suppressor role." (PMID 21364580, 2011). "Data presented here indicate the ability of hMena/hMena11a to sustain EGF and NRG1-mediated signalling responsible for a proliferative signature of breast cancer." (PMID 21209853, 2010). "Exogeneous overexpression of HER2 or stimulation by EGF and NRG1 of different breast cancer cell lines induce the up-regulation of hMena both at the mRNA and protein levels, which suggests a link between ErbB family activation and hMena." (PMID 21209853, 2010). "One such factor is the up-regulation of αvβ3 integrin in low HRG/NRG1-expressing breast cancer cell lines." (PMID 19775429, 2009). "Within the cohort, three patients diagnosed with breast cancer were found to have NRG1 fusions." (PMID 40730881, 2025). "The frequencies of NRG1 fusions across various cancer types were as follows: prostate cancer, 0.65%; breast cancer, 0.47%; lung cancer, 0.29%; esophageal cancer, 0.25%; colorectal cancer, 0.17%; gastric cancer, 0.13%; pancreatic cancer, 0.11%; and hepatocellular carcinoma, 0.05%)." (PMID 40730881, 2025). "Notably, the frequency of NRG1 fusion was greater in several other tumor types than in lung cancer, with values of 0.65% in prostate cancer and 0.47% in breast cancer." (PMID 40730881, 2025). "Comparing PDGFC expression across a broader range of breast cancer molecular subtypes, as well as evaluating the activity of the PDGFC/NRG1 signaling axis between tumor cells and fibroblasts, will provide valuable insights for the development of more precise therapeutic strategies in breast cancer." (PMID 41213930, 2025). "To assess the prognostic value of Nrg1 in breast cancer, we analyzed whether NRG1 is overexpressed in specific breast cancer subtypes." (PMID 36707514, 2023). "A similar paracrine role for stromal-derived NRG1 has been demonstrated in breast cancer." (PMID 36357571, 2023).